TLR9 (toll like receptor 9)
Diseases named in the same sentence as TLR9 in open-access papers (continued):
Sharing a sentence is not in itself a finding about the gene and the disease.
infection (continued). "At Day 3 post-infection in the footpad, CD11b+ DCs from CD11ccreIL-4Rα−/lox and littermate control mice expressed equivalent levels of TLR4 and TLR9." (PMID 32039054, 2019). "During infection, EBV expresses BGLF5, EBV lytic-phase protein, which contributes to downregulating TLR9 levels through RNA degradation." (PMID 31886298, 2019). "TLR-9 activation plays a primary role in MyD88 induction that is dependent on the synthesis of IL-12 and IFN-γ during T. cruzi experimental infection and contributes to the formation of a pro-inflammatory environment." (PMID 29599775, 2018). "Virulent IOE infection triggers upregulation of several TLRs in liver tissue of infected mice including TLR2, TLR7, and TLR9." (PMID 29049365, 2017). "EBV has been reported to induce an innate immune response characterized by strong release of IL-8 and MCP-1 via TLR9 and TLR2 in monocytes shortly after infection." (PMID 28245863, 2017). "We performed in vivo and in vitro experiments to show that pattern recognition receptors TLR7 and TLR9 are critical for the IFN-I response and host survival in the mouse model of infection." (PMID 27459510, 2016). "Interestingly, TLR9, discerning unmethylated CpG sequences and pathogen-derived DNA, was recently reported to mediate signaling for induction of IFNs and protection in EV71-infected mice by recognizing danger-associated molecular patterns released during infection." (PMID 27007979, 2016). "The innate cellular response to the initial stages of infection is mediated by Toll like receptor (TLR2, TLR4, TLR9) signaling, these receptors have been shown to recognize the surface proteins of CMV and RSV." (PMID 27340772, 2016). "For example, different strains of S. aureus can activate different pattern recognition receptor (PRR) signaling cascades, specifically NOD2/IRF5 versus TLR9/IRF1, leading to different type I IFN responses that affect survival after infection." (PMID 27143388, 2016). "Eight genes (NCF4, CD14, IL17D, CD1D, CD163, IL1R2, TLR9, and TLR2) with different expression in each infection group were selected for qPCR analysis." (PMID 25906258, 2015). "Activation of TLR9 apically on IEC prevents TLR4-induced gut leakiness and infection of IEC monolayers with Campylobacter jejuni disrupts the intestinal epithelial barrier function by reducing TLR9 expression at the surface membrane of IEC." (PMID 24600450, 2014). "The expression of MyD88, TLR9 and TLR7 (recently demonstrated as mediating the pDC response to LCMV) increased during LCMV-WE infection but only enabled infant pDCs to reach the levels observed at baseline in adult pDCs." (PMID 24376875, 2013). "However, the role of TLR9 during the infection by this fungus remains unclear." (PMID 23936560, 2013). "According to our previous data, a crucial role of TLR9 was evidenced in the establishment of Th1 response, whereas TLR2 appeared to act as immunoregulator in the early stage of infection." (PMID 23650544, 2013). "In vitro infection of human cervical epithelium with HSV-2 resulted in increased levels of TLR4 and TLR9 mRNA and a concomitant increase in protein expression for each TLR." (PMID 23061052, 2012). "Upon infection of primary bone marrow-derived macrophages (BMDMs), MCMV inhibited nuclear translocation of NF-κB p65 (RelA) after stimulation of TLR7 or TLR9." (PMID 22319449, 2012). "The resistance to infection with T. cruzi is known to depend on appropriate MyD88 signaling after stimulation of TLR2 and TLR9, and TLR4." (PMID 22348160, 2012). "Of note, human neutrophils express all TLRs, except TLR3, respond to TLR agonists, including TLR9, and TLR stimulated neutrophils recruit innate immune cells to sites of infection." (PMID 23028824, 2012). "In more recent studies, we determined that both DNA and RNA activate, respectively, TLR9 and TLR7 and are critical parasite components for induction of IL-12 and host resistance to a primary infection with T. cruzi." (PMID 22567144, 2012).
infection (continued). "In B lymphocytes, primary infection of EBV induces expression of TLR7 and downregulates expression of TLR9, as well as activates TLR7 signaling leading to expression of the downstream target IRF5 and cell proliferation." (PMID 21429244, 2011). "One study proved that the expression levels of TLR-2, TLR-4, TLR-9 and TLR-11 were significantly raised in mouse IECs following infection with Toxoplasma gondii on day 8 post-infection." (PMID 21943110, 2011). "infection with MHV-68, TLR9 seems to play a crucial role in spleens for an efficient viral control, but not in lungs after in." (PMID 21060793, 2010). "For HSV, TLR2, TLR3, TLR9, the MAVS pathways and the RNA polymerase III pathway have been identified as sensing the infection and inducing the production of IFN-α/β and cytokines." (PMID 21994567, 2009). "Effect sizes of louse infection grade on the most intense responses (TLR2 and TLR9) and on total TNF-α (summed over all receptor-ligand combinations), TIR, were striking." (PMID 19386086, 2009). "Cell lines expressing TLR9, permissive to infection by both adenoviral serotypes utilizing the Coxsackievirus-AdV Receptor (CAR) and serotypes utilizing CD46, show a preferential induction of TLR9-mediated events by AdVs utilizing CD46 for their entry." (PMID 19088911, 2008). "Studies have demonstrated that mice lacking TLR9 exhibit significantly increased bacterial loads and higher mortality rates upon infection with KP." (PMID 40140770, 2025). "We found that TLR2, TLR4, TLR9, and the TLR3/4 adaptor molecule TRIF are dispensable for inducing host resistance against the subsequent infection, as observed by reduced bacterial loads in the lung of mice that were first infected with Lp thyA L. pneumophila compared to mock." (PMID 40558085, 2025). "The DNA of Toxoplasma gondii can activate TLR9, yet dendritic cells (DCs) do not become activated during infection in the absence of IFN-γ, and non-infected DCs serve as the primary producers of IL-12 in this context." (PMID 40460068, 2025). "Of note, previous studies had shown that the immunomodulatory effects of CpG ODN extended to the CNS as cells in the CNS, (some of which expressed TLR9) responded by producing chemokines and cytokines in vitro and in vivo even in the absence of infection." (PMID 40059770, 2025). "The TLR9 and cGAS DNA pathways are two major signaling pathways detecting self and non-self DNA to mount immune responses against infection and tumorigenesis." (PMID 40337520, 2025). "These novel sequences offer enhanced protection against infection, but are not directly anti-microbial and do not appear to be stimulating the immune system via TLR9 or other key innate immune sensors, despite containing CpG motifs." (PMID 39492991, 2024). "Interestingly, seven weeks post infection, this pattern shifted, as BALB/c and C57BL/6 upregulated the expression of TLR2, TLR5, TLR8, TLR9, and MyD88 mRNA." (PMID 38896633, 2024). "Several TLRs, TLR3 and TLR9 can recognize viral nucleic acids or viral protein produced by PRRSV leading to release many cytokines, such as IL-6, TNF-α and IFN-γ at the early stage of infection." (PMID 37099541, 2023). "It is during ongoing infection that HPV employs several strategies to facilitate immune evasion, such as reducing the amount of antigen being produced during the early phase of infection, suppressing TLR9 expression in keratinocytes, and downregulating NF-κB." (PMID 37509353, 2023). "Besides increased expression of TLR-9 upon LdCen−/− immunization, we observed decreased expression of TLR-2 in APCs compared to LdWT infection." (PMID 37111420, 2023). "The level of TLR9 was 168%, p < 0.0001 at 3 h post JEV infection which dramatically increased with increasing time points post infection and reached to the level 414%, p < 0.0001 at 24 h post infection when compared to the level expressed at 0 h post JEV infection." (PMID 36707891, 2023).
infection (continued). "From these data, we conclude that TLR2 and TLR9 are partially responsible for infection-induced osteoclastogenesis in RANKL-primed cells, but TLR2- and TLR9-independent mechanisms contribute significantly to osteoclast formation during intracellular infection." (PMID 36226943, 2022). "To identify whether S. aureus can promote osteoclastogenesis through TLR2- or TLR9-indepenent mechanisms, we next studied the response of RANKL-primed osteoclast precursors to intracellular infection with WT S. aureus." (PMID 36226943, 2022). "Our prior shRNA KD of TLR9 in U937 cells also failed to reveal a required role for TLR9 at 24 to 72 h post infection." (PMID 34280250, 2021). "In particular, several studies have shown that TLR9 activation reduces EBV and MHV68 reactivation from a latent infection in B cells and EBV infection and/or replication in B cells and monocytes after a de novo infection." (PMID 34749760, 2021). "In their studies, infection of human primary B lymphocytes with EBV led to inhibition of TLR9 function, reducing the levels of mRNA and TLR9 protein, thus demonstrating that the virus decreases TLR9 level." (PMID 34439137, 2021). "Additionally, the coordination of signaling through TLR9 and cGAS pathways orchestrates production of type I IFN in response to infection with ectromelia virus (ECTV)." (PMID 34844429, 2021). "In contrast, KO of TLR9 did not change the production of either IL-6 or TNFα, indicating that, in human macrophages, TLR9 is not a relevant or important receptor during the early stages of intracellular infection." (PMID 34280250, 2021). "In contrast, efficient infection of pDCs through viral binding to the MHC class II molecule HLA-DR and expression of EBV genes was reported together with MHC class II-mediated uptake, degradation, and subsequent activation of TLR9 followed by IFN-α secretion." (PMID 33785626, 2021). "The absence of TLR9 decreases the host resistance to fungus, probably affecting the early stages of infection." (PMID 33446850, 2021). "Therefore, to identify the critical receptors upstream of MyD88, we investigated craniotomy infection in TLR2 and TLR9 knockout (KO) mice." (PMID 32290861, 2020). "We infected the NK92 cell line and primary NK cells with cell-free inocula of HHV-6A, HHV-6B or HHV-7 and evaluated TLR9, STING, and IFI16 pathway expression by Real-Time PCR, Western Blot, immunofluorescence and flow cytometry for 1, 2, 3, and 6 days post-infection." (PMID 32140147, 2020). "Although WT infection-specific regulation was observed only for TLR8 and IFNGR1, all four genes were expressed at higher levels (TLR8 and TLR9) or at lower levels (IFNGR1 and PYCARD) in the WT-infected dTHP1 cells than in the mock-treated or ΔrtxA1 mutant-infected dTHP-1 cells." (PMID 32817457, 2020). "Therefore, we examined the functional importance of both receptors in bacterial containment during S. aureus craniotomy infection using TLR2 and TLR9 KO mice." (PMID 32290861, 2020). "In order to address the question, if bacteria that show low intracellular CFUs already 2 h post-infection are degraded or not internalized, TLR9 studies with HEK-Blue hTLR9 cells were performed." (PMID 31057086, 2019). "However, infection of human primary keratinocytes with HPV16 inhibits TLR9 expression, where E6 and E7 oncoproteins directly down-regulate TLR9 at transcriptional level." (PMID 31337018, 2019). "Similarly, in our murine experiments, we noted that TLR9 gene expression is increased in lung leukocytes obtained by collagenase digestion and ficoll density separation 5 days post-PR8 infection while TLR4 is reduced." (PMID 30682165, 2019). "In the absence of PD0325901, exposure of pDCs to HSV-1 and HCMV results in a non-permissive infection and TLR9-mediated production of IFN-α." (PMID 29535732, 2018).
infection (continued). "Using two infection doses, 3 × 103 PFU and 106 PFU, data from the survival rates, pathology, and IFN-β induction of infected mice revealed the importance of Tlr9 in the resistance to mousepox, which is consistent with the recent finding that Tlr9 is the only TLR required for resistance to mousepox." (PMID 29963044, 2018). "In terms of TLR9+ expression, we identified stronger interactions with clinical infection by L. (L. ) amazonensis as opposed to the expressions of TLR2+ and 4+, indicated by greater expression in the ADCL/L." (PMID 29543867, 2018). "infection with HSV-2, and such control of viral replication requires TLR9 for maximal synergy." (PMID 29760708, 2018). "However, since Tip-DCs were also observed to exhibit T-cell stimulatory capacity in different infection models, the intrinsic ability of Tip-DCs derived from TLR2 and/or TLR9 KO mice to stimulate CD4+ and CD8+ T cells remains to be investigated." (PMID 29760708, 2018). "To determine whether this activation mechanism induced by TLR9 is shared with other TLR ligands, we determined both Th1 and Th17 responses in target organs of infection." (PMID 28280488, 2017). "TLR9 transcription was only upregulated in the early stages of infection in both these tissues when compared with healthy non-infected control dogs, while TLR9 down regulation was observed in lymph nodes and skin with disease progression." (PMID 27094260, 2017). "There was no significant change in pDC HLA-DR, CD86 or CD123 expression, either without stimulation (NIL) or following TLR7 or TLR9 stimulation, when baseline was compared to peak-infection in eight individuals." (PMID 28572564, 2017). "To investigate the involvement of AEP and cysteine proteases such as CatB, L and S on the development of cutaneous lesions following infection with L. major, we compared the footpad thickness between WT, AEP-/-, CatB-/-, CatL-/-, CatS-/- and TLR9-/- mice over a time-course of 49 days." (PMID 27182703, 2016). "In contrast, TLR9 was not expressed in the MAP condition until it became significantly down regulated in the late stage (720 minutes post infection)." (PMID 27653506, 2016). "We have now analyzed the role of TLR2, TLR4 and TLR9 in the control of B. microti infection and found that in vivo TLR2 and TLR4 cooperate to eliminate this pathogen, while TLR9 is dispensable to control the infection." (PMID 28119856, 2016). "In order to find out the role of TLR-mediated responses in the control of this pathogen, the course of infection of B. microti was analyzed over 3 weeks in wild-type (WT) and TLR knock out (KO) mice including TLR2−/−, TLR4−/−, TLR9−/−, TLR2×4−/− and TLR2×4×9−/−." (PMID 28119856, 2016). "TLR9−/− mice showed the same level of H. pylori colonization; however, the myeloperoxidase (MPO) activity and mRNA expression of TNF-α and IFN-γ were increased in the gastric tissue during the initial phase of infection." (PMID 25945326, 2015). "Following infection, we could ascertain that L. guyanensis isolates, regardless of their LRV burden, displayed similar disease evolution phenotypes in MyD88−/− and TLR9−/− mice." (PMID 24801628, 2014). "In the present study we show that the absence of TLR-9 does not protect mice from the development of acute ileitis following peroral infection with T. gondii." (PMID 24932221, 2014). "During infection, secreted TNF-α due to BAG-mediated TLR9 activation as well as activation by other components of B. anthracis might enhance LT-mediated macrophage cytotoxicity and eventually increases the lethality of mice." (PMID 25472474, 2014). "To investigate the potential effect of TLR9 in more detail, we next infected PBMCs in the presence of CpG A and the TLR9 antagonist TTAGGG ODN, which neutralize the stimulatory effect of CpG A. The ligands were added 2 hours post-infection with DENV." (PMID 23469297, 2013). "It is noteworthy that TLR-9 is known to be activated in response to scAAV2 infection but not against ssAAV2." (PMID 23320106, 2013).
infection (continued). "The increase of TLR9 expression observed in MHCII+CD11chigh cells contrasted with the decreased expression of this receptor in F4/80+CD11b+ and F4/80lowCD11b+ cells during infection." (PMID 23650544, 2013). "About 18% of F4/80+CD11b+ cells from Rec TLR9−/− mice were committed in IL-12/IL-23p40 production after CpG DNA addition during the infection versus 11% in non-infected Rec TLR9−/− mice." (PMID 23650544, 2013). "First, we assessed the impact of the absence of TLR2 or TLR9 on the percentage of TNF-α+ cells during the infection." (PMID 23650544, 2013). "A combined effect of the genotypes associated with increased risk of PTB (i.e. TLR9 1174G/G and IFNG 2109 A/A) was found when comparing PTB patients with LTBI controls (p=0.004) but not with healthy controls without infection (p=0.433)." (PMID 24176007, 2013). "Following intranasal immunization with (TS) in the presence of the TLR9 activator CpG ODN, the absence of CD4+ or CD8+ T cells renders the vaccinated animals completely susceptible to infection." (PMID 22496959, 2012). "A lack of TLR9 impairs clearance and decreases survival to C. neoformans challenge in an intranasal infection model." (PMID 23189270, 2012). "We found that poly(I∶C)- and LPS-stimulation of MDMs abrogated infection by CCR5-using, macrophage-tropic HIV-1, and by vesicular stomatitis virus glycoprotein-pseudotyped HIV-1 virions, while TLR2, TLR7 or TLR9 agonists only partially reduced infection to varying extent." (PMID 23028330, 2012). "Carabin could prevent the early activation of anergic or ignorant autoreactive B cells after infection-induced TLR, and notably TLR9, signaling." (PMID 23109291, 2012). "Accordingly, in vitro infection of Balb/c fibroblasts resulted in reduced proliferation rates whereas infection of TLR-9-/- fibroblasts did not." (PMID 21810214, 2011). "High level IL-12p40 production in ΔROP16 infection was dependent on the host cell adaptor molecule MyD88, but surprisingly was independent of any previously recognized T. gondii triggered pathway linking to MyD88 (TLR2, TLR4, TLR9, TLR11, IL-1ß and IL-18)." (PMID 21931552, 2011). "In non-infected non-CIC ArLa cell low level of TLR9 expression was seen localized in the ER and upon infection TLR9 was upregulated and localized in endosomes, indicating normal trafficking of the protein." (PMID 21079774, 2010). "Impaired classical activation of macrophages (as manifest by constitutive ex-vivo expression of iNOS) was observed in cells from all mutant mouse strains post infection, but most prominent in macrophages with defective TLR9 signaling (either TLR9−/− or TLR4lps-d/TLR9−/− cells)." (PMID 20360853, 2010). "In normal mammary tissue CD44+/CD24−/low stem cells TLR9 localized in endosomes in Ad5/3-Delta24 infected cells, as indicated by colocalization with an endosomal marker EEA1 and persisted still in the endosomes 6 h after infection." (PMID 21079774, 2010). "Colocalization analysis of TLR9 to endosomal marker EEA1 in infected ArLa non-CIC showed that TLR9 partially colocalizes with endosomes at two hours and fully four hours after infection." (PMID 21079774, 2010). "In LMMs with untransformed TLR variables as the response, the predicted reductions in TNF-α production in mice in the highest louse infection category in relation to mice uninfected with lice were 49% for TLR2/HKLM, 55% for TLR2/zymosan, 59% for TLR9 and 56% for TIR." (PMID 19386086, 2009). "In an MCMV-infected C57BL/6J mouse, the induction of type I IFN occurring 36 hours post-infection depends on pDCs and requires TLR9 sensing and MyD88 signaling, but not TLR7 recognition." (PMID 21994556, 2009). "Consistent with IFN-I production, the absence of TLR9 did not increase survival following infection with L. monocytogenes." (PMID 19325882, 2009).